SPHK1 (sphingosine kinase 1)
Diseases named in the same sentence as SPHK1 in open-access papers (continued):
Sharing a sentence is not in itself a finding about the gene and the disease.
liver fibrosis (20 papers, 2016 to 2025). "The effects of Sal on SphK/S1P/S1PRs signal pathway in mouse with liver fibrosis caused by CCl4 and how it regulates the migration and activation of LX-2 induced by exosomal SphK1 from LSECs were explored in this study in vivo and in vitro, respectively." (PMID 34054552, 2021). "In reports where LSECs secreted high levels of SphK1 in exosomes in CCl4-induced hepatic fibrosis, facts were demonstrated that Sal was able to hamper LX-2 activation by SphK1 in exosomes via blocking the activation of the AKT pathway." (PMID 40761743, 2025). "CDD induced MASH and liver fibrosis were accompanied by elevated levels of S1P and increased expression of SphK1 in capillarized liver sinusoidal endothelial cells (LSECs) in mice." (PMID 38753743, 2024). "The expression and activity of SphK1 are significantly increased in fibrotic livers compared to normal livers, and SphK1 can promote liver fibrosis by modulating collagen deposition and α-SMA223." (PMID 37258585, 2023). "Sphingosine kinase 1 (SphK1) plays critical roles in the activation of HSCs and liver fibrosis, and SphK1 was strongly induced in mice exposed to CCl4." (PMID 35186191, 2022). "In this study, serum exosomes derived from liver cirrhosis patients or mice with liver fibrosis released high concentrations of SphK1 and promoted HSC migration." (PMID 34054552, 2021). "A similar remarkably high expression of SphK1 in the serum exosomes derived from mice with liver fibrosis was recorded (p < 0.01)." (PMID 34054552, 2021). "PF543 is a potent and specific inhibitor of SphK1 useful for identifying specific roles of SphK1-driven S1P signaling, which has shown an inhibitory action on liver fibrosis through the S1P pathway." (PMID 28890699, 2017). "Recently developed HCV treatments involving direct-acting antivirals can eliminate HCV in more than 95% of patients, and amelioration of liver fibrosis would be expected after HCV elimination due to the subsequent reduction in SPHK1." (PMID 29208982, 2017). "Collectively, the analysis of human liver tissues suggests that SPHK1 plays an important role in the progression of liver fibrosis." (PMID 29208982, 2017). "Taken together, these data suggest that HuR binds to SphK1 mRNA and enhances the stability of SphK1 mRNA during liver fibrosis." (PMID 26912347, 2016). "We observed a correlation between SphK1 mRNA expression and liver fibrosis in MASH livers." (PMID 38753743, 2024). "It is reported that PD could attenuate the proliferation and activation of HSCs via inhibiting SphK1 signaling pathway in CCl4-induced mice, contributing to the suppression of liver fibrosis." (PMID 35186191, 2022). "In addition, polydatin attenuated the activity of hepatic stellate cells (HSCs) through its antioxidant activity on sphingosine kinase 1 (SphK1) signaling to ameliorate mice liver fibrosis induced by carbon tetrachloride (CCl4)." (PMID 36235012, 2022). "The concentration of SphK1 was amplified in primary LSECs of liver fibrosis mice." (PMID 34054552, 2021). "High levels of SphK1 were detected in primary mouse LSECs of liver fibrosis mice." (PMID 34054552, 2021). "Likewise, the SphK1 expression and its product S1P were recorded to increase progressively as the liver fibrosis advanced in the bile duct ligation (BDL) and carbon tetrachloride (CCl4)-induced liver fibrosis, mouse model." (PMID 34054552, 2021). "High quantities of SphK1 expression have been shown recently to aid in the progression of liver fibrosis, whereas SphK1 inhibition substantially reduces the degree of liver fibrosis." (PMID 34054552, 2021). "A study used CCL4 to establish a liver fibrosis model and found that melatonin treatment not only reduces the degree of fibrosis, but also inhibits the SphK1/S1P signaling pathway both in vitro and in vivo, thus confirming the hypothesis." (PMID 30687087, 2018).
liver fibrosis (continued). "In the present study, we compared the mRNA levels of SPHK1 in HCV-infected human liver between two groups, those with severe liver fibrosis and those with mild liver fibrosis, finding that the SPHK1 mRNA level was significantly higher in severe fibrosis than in mild fibrosis." (PMID 29208982, 2017). "Considering the key role of HSC in liver fibrosis, LX-2 was treated with PMA (an agonist of SphK1) and/or Sal." (PMID 34054552, 2021). "In a more recent study it became apparent that SPHK1-induced CCL2 secretion from Kupffer cells activated fibroblasts and thereby fostered progression of liver fibrosis." (PMID 31379883, 2019). "Considering the special anatomical position of LSEC and HSC and the essential role of the interaction between LSECs and HSC in the process of liver fibrosis, we cultured the primary LSEC and detected its expression of SphK1, trying to prove the source of SphK1." (PMID 34054552, 2021). "This study was to explore the influences of Sal on the SphK/S1P/S1PRs signaling pathway in liver fibrosis induced by carbon tetrachloride (CCl4) in vivo, and investigated the mechanism of Sal affecting the migration and activation of HSC triggered by exosomal SphK1 in vitro." (PMID 34054552, 2021).
breast tumors (19 papers, 2012 to 2024). "Correlation analysis revealed that the level of SPNS2 were positively associated with SPHK1 levels in breast tumor tissues (***p < 0.0001)." (PMID 36309544, 2022). "Moreover, SphK1 high expression was inversely associated with both ER-positivity (p < 0.001) and PR-positivity (p = 0.003) in breast tumors which supports literature findings." (PMID 29207959, 2017). "Our results show that the expression of sphingosine kinase 1 (Sphk1) is increased in breast tumors after inoculation with M. globosa." (PMID 39235230, 2024). "BML-258 has been shown to inhibit SphK1 and decrease growth, size, and metastasis of the breast tumors." (PMID 33758708, 2021). "The levels of SPHK1 in breast tumor tissues were found to be significantly higher than the adjacent normal tissues in both the cohorts." (PMID 32170160, 2020). "We performed comparative analysis of SPHK1 expression using real time polymerase chain reaction (RT-PCR) on breast tumor tissues and adjacent normal breast tissues of 32 patients." (PMID 25153718, 2014). "Furthermore, HER2-negative ER+ breast tumors with high SphK1 expression demonstrated resistance to chemotherapy and poor prognosis." (PMID 29385066, 2018). "Increased SphK1 levels were detected in advanced and metastatic breast tumors in vivo." (PMID 29385066, 2018). "Sphingosine kinase 1 expression is also higher in ER– compared with ER+ breast tumours." (PMID 22460268, 2012). "Studies have reported that SPHK1 expression is increasing in trend along with the advancement of breast tumor staging; while basal-like triple negative breast cancer (TNBC) tumors exhibit the highest levels of SPHK1 when compared to other subtypes." (PMID 34820423, 2021). "Among the breast tumor cell lines, the metastatic and triple-negative MDA-MB-231 cells exhibited the highest SPHK1 protein expression and the most pronounced SPHK1 activity." (PMID 25153718, 2014). "It is conceivable that SPHK1 may exert roles in the enrichment and/or maintenance of breast CSC subpopulation, conferring the breast tumor with enhanced tumorigenicity and resistance towards oncology treatment, and thus leading to relapse and metastasis." (PMID 34820423, 2021). "Although the mechanisms of more highly SPHK1 expression in negative receptors of breast tumor is unclear, it can be due to its higher proliferation activity, which is consistent with the anti-apoptotic effect of S1P." (PMID 29531546, 2017). "As the expression of SPHK1 is associated with resistance to radiation and chemotherapies, using SPHK1 inhibitors and its specific analogs can be effective in the treatment of ER negative breast tumors." (PMID 29531546, 2017). "As none of these studies further stratified these SPHK1-expressing breast tumors based on CSC markers, the contribution of SPHK1 towards breast CSCs could be largely overlooked." (PMID 34820423, 2021).
pancreatic cancer (17 papers, 2016 to 2024). "ROC curves showed that SPHK1 combine with HAS2 has good diagnostic value in pancreatic cancer patients with 85% sensitivity and 99.4% specificity." (PMID 33506044, 2021). "The use of a SphK1−/− mouse model proved that SphK1-produced S1P promotes pancreatic cancer progression." (PMID 38203299, 2023). "Elevated SphK1 was found to be a characteristic of many pancreatic adenocarcinoma ductal lesions, with SphK1 thus being cited as a potential prognostic marker for pancreatic cancer." (PMID 35158806, 2022). "It was reported that the activated SPHK1/Akt/NF-κB signaling pathway promoted cell proliferation, cell cycle G1/S transition and reduced the apoptosis and chemosensitivity of pancreatic cancer cells." (PMID 36361531, 2022). "In other studies, LINC00173 was reported to inhibit pancreatic cancer by repressing sphingosine kinase 1 protein expression." (PMID 36213821, 2022). "The representative images indicated that SPHK1 protein expression was strongly enhanced in metastatic pancreatic cancer tissues compared with normal pancreatic tissue." (PMID 33506044, 2021). "The diagnostic ROC analysis of SPHK1 and HAS2 in TCGA cohort showed that SPHK1 and HAS2 can serve as potential diagnostic biomarkers for pancreatic cancer (P < 0.05)." (PMID 33506044, 2021). "Most importantly, both SPHK1 and HAS2 were significantly associated with short OS of pancreatic cancer patients." (PMID 33506044, 2021). "Kaplan-Meier analysis showed that increased expression of SPHK1 and HAS2 was associated with short overall survival (OS) of pancreatic cancer patients." (PMID 33506044, 2021). "Kaplan-Meier survival analysis and ROC curve were used to evaluate the prognostic and diagnostic roles of SPHK1 and HAS2 in pancreatic cancer." (PMID 33506044, 2021). "Kaplan-Meier analysis showed that increased expression of SPHK1 and HAS2 was significantly associated with short overall survival (OS) of pancreatic cancer patients." (PMID 33506044, 2021). "We observed the protein expression of SPHK1 in pancreatic cancer and normal pancreatic tissues using immunohistochemical staining on the Human Protein Atlas." (PMID 33506044, 2021). "The S1P/SPHK1 axis has also been reported earlier to promote the pancreatic cancer growth by regulating the expression of pancreatic stellate cells." (PMID 32170160, 2020). "Using a SphK1−/− mouse model, it has been demonstrated that S1P generated by SphK1 promotes pancreatic cancer progression." (PMID 29269995, 2017). "We previously constructed a lentiviral expression vector that stably overexpresses SPHK1 in pancreatic cancer cells." (PMID 27811359, 2016). "Elevated SPHK1 levels have been associated with resistance to imatinib in chronic myeloid leukemia (CML) and resistance to gemcitabine in pancreatic cancer cell." (PMID 27811359, 2016). "The results revealed that pancreatic cancer patients with high expression of SPHK1 had shorter OS than patients with low SPHK1 expression (P = 0.037), and pancreatic cancer patients with high HAS2 expression had shorter OS than patients with low expression of HAS2 (P = 0.0074)." (PMID 33506044, 2021). "However, the result demonstrated that pancreatic cancer patients with high SPHK1 expression were significantly related to the location of tumor in the pancreas (P = 0.007), clinical stage (P = 0.013), and tumor status (stage T, P = 0.03)." (PMID 33506044, 2021). "Notably, in the present study, three pancreatic cancer cell lines were selected for evaluating the SPHK1 and HAS2 expressions." (PMID 33506044, 2021). "Similarly, miR-506 downregulation increased SphK1 expression and promoted pancreatic cancer progression." (PMID 33465049, 2021). "Furthermore, the combination of SPHK1 and HAS2 could be an effective diagnostic marker for the pancreatic cancer." (PMID 33506044, 2021). "The present study examined the expression of SPHK1 and HAS2 in pancreatic cancer tissues and cell lines, respectively." (PMID 33506044, 2021).
pancreatic cancer (continued). "In conclusion, this study demonstrated for the first time that the expression of SPHK1 and HAS2 was markedly increased in pancreatic cancer." (PMID 33506044, 2021). "The prognostic effects of SPHK1 and HAS2 for overall survival (OS) of pancreatic cancer patients were evaluated by Kaplan-Meier survival analysis and the log-rank tests." (PMID 33506044, 2021). "This study is aimed at investigating the expression of SPHK1 and HAS2 on the prognosis of pancreatic cancer." (PMID 33506044, 2021). "To further verify the expression of SPHK1 and HAS2 in pancreatic cancer, we detected the mRNA and protein expressions of SPHK1 and HAS2 in pancreatic cancer cell lines." (PMID 33506044, 2021). "The results showed that SPHK1 and HAS2 expressions were increased in pancreatic cancer tissues compared with normal tissues." (PMID 33506044, 2021). "The results showed that the mRNA expression of SPHK1 and HAS2 was significantly higher in pancreatic cancer group (177 cases) than those of the healthy control (173 cases) (P < 0.05 and P < 0.05), respectively." (PMID 33506044, 2021). "The possible potential application of SPHK1 and HAS2 in distinguishing pancreatic cancer was further explored." (PMID 33506044, 2021). "According to the median values of SPHK1 and HAS2 expressions, pancreatic cancer patients were divided into high and low SPHK1 and HAS2 expression groups." (PMID 33506044, 2021). "The expression of SPHK1 and HAS2 was markedly upregulated in pancreatic cancer tissue and cell lines, respectively." (PMID 33506044, 2021). "Consistently, the expression of SPHK1 and HAS2 in pancreatic cancer cell lines was significantly increased." (PMID 33506044, 2021). "In this study, we analyzed the expression and clinical significance of SPHK1 and HAS2 in pancreatic cancer." (PMID 33506044, 2021). "Then, Spearman correlation analysis was performed, and the results indicated that there is a significantly positive correlation between the expression of SPHK1 and HAS2 in pancreatic cancer." (PMID 33506044, 2021). "We have verified that the expression of SPHK1 and HAS2 was markedly increased in pancreatic cancer tumor tissues." (PMID 33506044, 2021). "The expression of SPHK1 and HAS2 in pancreatic cancer tissues was analyzed through TCGA and GTEx databases and validated by qRT-PCR and Western blot in pancreatic cancer cell lines." (PMID 33506044, 2021). "The protein expression of SPHK1 and HAS2 was validated by Western blot, and the results showed that the levels of SPHK1 and HAS2 protein were markedly elevated in pancreatic cancer cell lines compared with normal pancreatic duct epithelial cell line." (PMID 33506044, 2021). "However, the expression and clinical significance of SPHK1 in pancreatic cancer remain unknown." (PMID 33506044, 2021). "Then, we investigated the correlation of the SPHK1 and HAS2 expressions with clinical characteristic in pancreatic cancer." (PMID 33506044, 2021). "In pancreatic cancer, the overexpression of miR-506 blocks the SPHK1/AKT/NF-κB signaling pathway and inhibits pancreatic cancer metastasis." (PMID 31803739, 2019). "In addition, miRNA-613 targets Sphk1 and inhibits bladder cancer cell proliferation, and miR-506 suppresses liver cancer angiogenesis by targeting Sphk1 mRNA, downregulated miR-506 expression facilitates pancreatic cancer progression and chemoresistance via Sphk1/Akt/NF-κB signaling." (PMID 28991193, 2017). "Conversely, inhibiting SPHK1 can sensitize CML and pancreatic cancer cells to the proapoptotic effects of imatinib and gemcitabine, respectively, apparently by reducing the S1P/ceramide ratio." (PMID 27811359, 2016). "The possible correlation between SPHK1 and HAS2 expressions in pancreatic cancer was also analyzed." (PMID 33506044, 2021). "However, the expression of SPHK1 and HAS2 was more easily detected in the advanced stages of pancreatic cancer." (PMID 33506044, 2021).
pancreatic cancer (continued). "The increased expression of SPHK1 and HAS2 in pancreatic cancer implied that SPHK1 and HAS2 may be essential for the progression of pancreatic cancer." (PMID 33506044, 2021). "Our data showed that the epithelioid-derived PANC-1 expressed more SPHK1 and HAS2, compared to these metastatic site-derived Capan-1 and AsPC1, suggesting that SPHK1 and HAS2 may be related to the origin of pancreatic cancer cell lines." (PMID 33506044, 2021). "The common signaling pathway of SPHK1 and HAS2 in pancreatic cancer might be responsible for cancer progression." (PMID 33506044, 2021). "The results of GO and KEGG analyses suggested that SPHK1 and HAS2 might play important roles in pancreatic cancer cell proliferation and invasion." (PMID 33506044, 2021). "Therefore, we analyzed TCGA and GTEx databases to evaluate the expression of SPHK1 and HAS2 in pancreatic cancer." (PMID 33506044, 2021). "Additionally, Spearman correlation analysis was applied to assess the correlation between the SPHK1 and HAS2 in pancreatic cancer." (PMID 33506044, 2021). "HAS2 is well known in various tumor invasions, so the interaction of SPHK1 and HAS2 might exert a pivotal role in pancreatic cancer progression." (PMID 33506044, 2021). "Furthermore, the potential prognostic roles of SPHK1 and HAS2 in pancreatic cancer patients were evaluated." (PMID 33506044, 2021). "Therefore, it is clinically possible to detect SPHK1 and HAS2 to improve the diagnosis and prognosis of pancreatic cancer." (PMID 33506044, 2021). "Overexpression of SPHK1 and HAS2 could be important markers for the prognosis of pancreatic cancer." (PMID 33506044, 2021). "Thus, SPHK1 and HAS2 might be useful prognostic biomarkers for pancreatic cancer and worthy of further study before their use in clinical practice." (PMID 33506044, 2021). "Thus, we consider that SPHK1 and HAS2 may be potential biomarkers for pancreatic cancer diagnosis." (PMID 33506044, 2021). "Thus, SPHK1 and HAS2 might not be ideal biomarkers in the detection of early-stage pancreatic cancer." (PMID 33506044, 2021). "However, it should be noted that SPHK1 and HAS2 might not be sensitive in the early diagnosis of pancreatic cancer." (PMID 33506044, 2021).